GDF15 (growth differentiation factor 15)
Diseases named in the same sentence as GDF15 in open-access papers (continued):
Sharing a sentence is not in itself a finding about the gene and the disease.
pulmonary fibrosis (continued). "The study suggested that increased expression and accumulation of GDF-15 in the extracellular matrix contribute to the fibrotic process in idiopathic pulmonary fibrosis." (PMID 38672115, 2024). "Similary, in idiopathic pulmonary fibrosis (IPF), an aggressive ILD associated with aging, GDF15 expression has been linked to disease severity, exacerbation, and prognosis." (PMID 38195721, 2024). "In this study, GDF15 expression is induced by imperatorin, which in turn decreases the expression of pro-fibrotic markers, exerting a beneficial effect against pulmonary fibrosis." (PMID 38111379, 2023). "Our data suggest that GDF15 mediates lung fibrosis through fibroblast activation and differentiation, implicating a potential direct role of this matrix-associated cytokine in promoting aberrant cell responses in disease." (PMID 35993367, 2022). "In vivo, when GDF15 was neutralized from 14 days and onward after initiation of bleomycin-induced lung fibrosis, we observed significantly less lung fibrosis, most notably due to decreased collagen deposition in fibrotic tissue areas." (PMID 35993367, 2022). "In vivo, GDF15 neutralization in a bleomycin-induced lung fibrosis model led to significantly less fibrosis." (PMID 35993367, 2022). "In order to determine the effect of GDF15 neutralization in vivo, we employed a bleomycin-mediated lung fibrosis model in mice and administered anti-GDF15 monoclonal antibody 14 days after initiation of injury." (PMID 35993367, 2022). "Here, we determined that mice treated with anti-GDF15 mAb had significantly lower lung fibrosis, as measured by total lung hydroxyproline, a major component of collagen." (PMID 35993367, 2022). "GDF-15 expression is induced during fibrosis development, and serum levels correlated strongly with clinical symptoms of lung fibrosis, which was the case in a previous study as well as in our baseline study." (PMID 34830647, 2021). "When we interrogated the function of these genes further, we found that many of them (e.g., MMP7, GDF15, and MUC5B) have been implicated in the pathogenesis of pulmonary fibrosis." (PMID 33082228, 2020). "GDF15 levels were also increased in patients with systemic sclerosis and correlated with clinical symptoms of lung fibrosis and deterioration in lung function." (PMID 33344478, 2020). "Similar results were reported in a bleomycin model of pulmonary fibrosis, GDF15 expression was increased in the lung, bronchoalveolar lavage fluid and plasma and was associated with markers of cellular senescence in alveolar epithelial cells." (PMID 33344478, 2020). "We discovered two fibroblast-inhibiting cytokines, CST3 and GDF15, from normal epithelial cells and demonstrated their therapeutic effects in a bleomycin-induced pulmonary fibrosis mouse model." (PMID 29724997, 2018). "In vivo, GDF15 neutralization in a bleomycin-induced lung fibrosis model attenuated fibrosis." (PMID 40565178, 2025). "While clinical trials with patients suggested GDF15 as a novel predictive biomarker of lung fibrosis progression, contemporary mechanistic studies in vitro and animal fibrosis models showed that GDF15 facilitates lung fibrosis by activating macrophages and fibroblasts." (PMID 40565178, 2025). "GDF-15 may serve a reliable marker for the detecting fibrosis in HP and could be a potential therapeutic target for the treating pulmonary fibrosis." (PMID 38195721, 2024). "GDF15 may aggravate the inflammatory response of the lung tissue and accelerate the process of pulmonary fibrosis by promoting ferroptosis, which may be related to the ability of members of the TGF-β superfamily to promote ferroptosis in tumour cells." (PMID 37093513, 2024). "Moreover, elevated levels of GDF15 were detected in the lung homogenates of patients with idiopathic pulmonary fibrosis, indicating its potential role as a biomarker of pulmonary fibrosis." (PMID 38132468, 2023). "Blocking GDF15 in vivo inhibited bleomycin-induced lung fibrosis." (PMID 35993367, 2022).
pulmonary fibrosis (continued). "GDF-15 is an epithelial stress marker that is elevated in patients with idiopathic pulmonary fibrosis (IPF), a predictor of more severe disease and worse outcomes in IPF and associated with a greater odd of developing interstitial lung abnormalities (ILA) in both the FHS and COPDGene cohorts." (PMID 35390066, 2022). "Macrophages are considered crucial regulators of lung fibrosis and are often found in close proximity to collagen-producing myofibroblasts, where they can secrete numerous profibrotic soluble mediators, potentially including GDF15." (PMID 35993367, 2022). "However, the expression of GDF-15 in patients with acute exacerbation of idiopathic pulmonary fibrosis (AE-IPF) is unclear." (PMID 35784345, 2022). "To summarize, we have shown for the first time to our knowledge that direct GDF15 neutralization could have a therapeutic effect in the treatment of lung fibrosis." (PMID 35993367, 2022). "The initial Cox proportional hazards model revealed that CKD (HR 28.13, 95%CI 4.84–163.38, p = 0.0002), HRCT lung fibrosis (HR 4.36, 95%CI 1.04–18.26, p = 0.045) and GDF-15 concentration (unit HR 1.0006, 95%CI 1.0002–1.0010, p = 0.003) were independent predictors of MACE occurrence." (PMID 34599271, 2021). "Collectively, recombinant CST3 and GDF15 could be developed as potential biopharmaceuticals for treating pulmonary fibrosis." (PMID 29724997, 2018). "did not observe differences in the development of pulmonary fibrosis between wild-type and GDF15-deficient mice." (PMID 26276681, 2015). "Therefore, considering the implication of GDF15 in lung fibrosis, we hypothesized that elevated baseline plasma concentrations of GDF15 could serve as a differentiating factor between fHP and non-fHP phenotypes." (PMID 38195721, 2024). "Our data suggest that GDF15 may also contribute to the progression of lung fibrosis." (PMID 35993367, 2022). "However, Gdf15 is dispensable for bleomycin-induced pulmonary fibrosis in mice." (PMID 31432710, 2019). "Recent studies have shown that GDF15, one of the most significantly upregulated proteins in IPF lung‐derived ECM, mediates pulmonary fibrosis through fibroblast activation and differentiation." (PMID 41409095, 2025). "Multivariable logistic regression analysis identified elevated GDF15 and impaired functional performance (TUG) as independent predictors of mortality in patients with idiopathic pulmonary fibrosis." (PMID 40944130, 2025). "CAV1, NOS2, GDF15, and CDKN2A were demonstrated to be influencing the development of pulmonary fibrosis by regulating ferroptosis." (PMID 35069688, 2021). "GDF15 neutralization in bleomycin-induced lung fibrosis in mice ameliorated fibrosis, whereas recombinant GDF15 (rGDF15) stimulated α-smooth muscle actin expression in normal human lung fibroblasts." (PMID 40565178, 2025). "CAV1, NOS2, GDF15, CDKN2A may influence the development of pulmonary fibrosis by regulating ferroptosis." (PMID 35069688, 2021). "However, GDF15 has also been proposed as a potential therapeutic agent for IPF, as it could ameliorate pulmonary fibrosis by inhibiting the TGF-β signalling pathway." (PMID 37093513, 2024). "Therefore, although the mechanism of GDF15 in pulmonary fibrosis is not yet clear, current evidence and technology enable its application as a biomarker for the diagnosis and prognosis of IPF and show its potential as a therapeutic target for IPF." (PMID 37093513, 2024). "Interestingly, a previous study reported that Gdf15–/– mice did not have reduced bleomycin-induced lung fibrosis." (PMID 35993367, 2022).
renal dysfunction (29 papers, 2013 to 2026). "In our own laboratory, we demonstrated that during cardiac surgery associated with cardiopulmonary bypass (CPB), circulating GDF15 levels increased and were associated with markers of cardiac injury and renal dysfunction." (PMID 34445593, 2021). "Recent studies have identified a strong association between GDF-15 levels and renal dysfunction, and it has been reported that increased preoperative GDF-15 levels can predict AKI risk after CABG." (PMID 34063283, 2021). "Previous reports have shown that GDF15 levels reflect progressive patients’ functional impairment (including muscle wasting) and renal dysfunction, being associated with both aging and, independently, with frailty indices (not including the Katz Score)." (PMID 32957481, 2020). "During cardiac surgery associated with CPB, GDF-15 levels increased substantially and were associated with markers of cardiac injury and renal dysfunction." (PMID 25171167, 2014). "In conclusion, in elderly men, GDF-15 improves prognostication of both cardiovascular, cancer mortality and morbidity beyond established risk factors and biomarkers of cardiac, renal dysfunction and inflammation." (PMID 24312445, 2013). "From a cohort of 1004 70-year old community-dwelling subjects we previously reported that the GDF-15 level was associated with cardiovascular risk factors, myocardial and renal dysfunction and indicators of inflammation, vascular dysfunction and plaque burden." (PMID 24312445, 2013). "Both cardiac as well as renal dysfunction are associated with higher GDF-15 levels." (PMID 35906276, 2022). "GDF-15 may be a novel biomarker for identify high-risk patients with muscle wasting and renal dysfunction before cardiovascular surgery." (PMID 31581569, 2019). "Thus, serum GDF-15 concentration may be a novel biomarker for identifying high-risk patients with muscle wasting and renal dysfunction in cardiovascular surgery patients." (PMID 31581569, 2019). "Thus, GDF-15 may be a novel biomarker for identifying high-risk patients with muscle wasting and renal dysfunction in cardiovascular surgery patients." (PMID 31581569, 2019). "We provided the first evidence that GDF-15 may be a novel biomarker for identifying high-risk patients with muscle wasting and renal dysfunction, compared with tumor necrosis factor α (TNFα) or insulin growth factor-1 (IGF-1) in cardiovascular surgery patients." (PMID 31581569, 2019). "Collectively, these results underscore the relationship between GDF-15 and biochemical indicators of renal dysfunction, hepatic enzyme activity, and systemic inflammation." (PMID 40731746, 2025). "They include hs-TnI/T and sST2, and to a lesser extent galectin-3, GDF-15 and some markers of renal dysfunction." (PMID 33852110, 2022). "Other biomarkers evaluated as predictors of adverse outcome are galectin-3, growth differentiation factor 15, mid-regional pro-adrenomedullin, and makers of renal dysfunction." (PMID 33852110, 2022). "GDF-15 is suggested to be a marker of cardiac injury and renal dysfunction in patients undergoing cardiac surgery." (PMID 33134397, 2020). "We concluded that preoperative GDF-15 levels reflect muscle wasting as well as renal dysfunction in preoperative cardiovascular surgery patients." (PMID 31581569, 2019). "An elevated GDF-15 level reflects muscle wasting as well as renal dysfunction in preoperative cardiovascular surgery patients." (PMID 31581569, 2019). "Moderate and statistically significant positive correlations were also observed between GDF15 and BUN (r = 0.57143, p = 0.04134) and serum creatinine (r = 0.62088, p = 0.02354), demonstrating that GDF15 levels are related to parameters reflecting renal dysfunction." (PMID 40941711, 2025). "This study concluded that GDF-15 levels might be used as a marker of cardiac injury and renal dysfunction." (PMID 26273671, 2015).
renal dysfunction (continued). "Importantly, the observed association between increased GDF-15 concentrations and a higher risk of dying from all causes was independent not only of well-known potential confounders like traditional CVD risk factors or markers of renal dysfunction." (PMID 32993054, 2020). "We observed that plasma levels of GDF-15 and TFF3 are potential renal dysfunction markers in Chinese SLE patients." (PMID 33134397, 2020). "In conclusion, our data suggest that plasma levels of GDF-15 and TFF3 are potential renal dysfunction markers in SLE patients, but plasma levels of these cytokines were weakly or not correlated with the SLEDAI-2K." (PMID 33134397, 2020). "Our data suggest that plasma levels of GDF-15 and TFF3 are potential renal dysfunction markers in SLE patients, but plasma levels of these cytokines are not correlated with the SLEDAI-2K." (PMID 33134397, 2020). "Moreover, plasma levels of GDF-15 and TFF3 were highly positively correlated with clinical parameters of renal dysfunction." (PMID 33134397, 2020). "However, when combined with GDF-15, the predictive ability was markedly improved for any kind of AKI and especially for AKI-3, as the most severe stage of postoperative renal dysfunction." (PMID 27717384, 2016). "Although the roles of GDF-15 and TFF3 in SLE were not clear, our results suggest that the plasma levels of GDF-15 and TFF3 reflect the severity of renal dysfunction in SLE." (PMID 33134397, 2020).
multiple myeloma (28 papers, 2015 to 2025). "Increased levels of circulating GDF15 are seen in patients with various types of cancer including myeloproliferative neoplasms and in multiple myeloma increased GDF15 is associated with poor prognosis." (PMID 37051288, 2023). "Our study examined an ambulatory care sample of patients with MM, demonstrating that serum GDF-15 concentrations are significantly associated with myeloma characteristics, even in a diverse clinical population at various stages of disease (though the majority was in stage I according to ISS)." (PMID 33144847, 2020). "Further understanding of whether and if the central (GFRAL) and peripheral (local, fast-acting) GDF-15-associated mechanisms exist and interact with myeloma biology is warranted." (PMID 33144847, 2020). "A randomized controlled trial with 309 AL amyloidosis patients concluded that GDF-15 level >7575 pg/mL predicted early mortality." (PMID 39781722, 2025). "In a study, circulating levels of GDF-15 were measured in AL amyloidosis patients before and at 3 and 6 months after treatment initiation." (PMID 39781722, 2025). "GDF15 was also reported to uncouple bone formation from resorption in myeloma patients with osteolytic bone disease." (PMID 39668628, 2024). "Another independent group has investigated the role of GDF-15 as surrogate or additive prognostic biomarker in AL amyloidosis patients." (PMID 34681575, 2021). "Taken together, the data presented in the literature support the relationship of GDF-15 with myeloma burden and disease progression." (PMID 33144847, 2020). "Growth differentiation factor 15 (GDF-15), a member of the transforming growth factor-β superfamily, participates in processes associated with myeloma development and its end-organ complications." (PMID 33144847, 2020). "Further in vitro experiments showed promotion of osteoclast differentiation and osteoblast inhibition, which together supports the role of GDF15 in another cardinal myeloma feature—bone disease." (PMID 33144847, 2020). "Our results suggest that serum GDF-15 reflects myeloma burden and shares a relationship with several markers of prognostic significance, as well as major manifestations." (PMID 33144847, 2020). "Earlier studies in newly diagnosed myeloma patients have established GDF-15 as a promising molecule of prognostic significance, with the potential to identify patients with poor response to therapy and worse prognosis (J.)." (PMID 33144847, 2020). "In AL amyloidosis, serum GDF-15 was recently revealed as the most significant prognostic measure for dialysis and a valuable addition to renal risk stratification." (PMID 33144847, 2020). "Abnormal secretion of GDF15 is observed from bone marrow stromal cells (BMSCs), and studies have focused on the unique role of the myeloma microenvironment in promoting clonogenic growth and self-renewal via GDF15." (PMID 31683939, 2019). "Two novel biomarkers, sST2 and GDF-15, showed satisfactory prognostic value for overall survival of AL amyloidosis patients." (PMID 31434944, 2019). "Further study in a larger independent AL amyloidosis population is needed to fully validate and confirm our findings indicating that measurement of sST2 and GDF-15 provides additional prognostic value in AL patients with cardiac involvement." (PMID 31434944, 2019). "In conclusion, the novel biomarkers sST 2 and GDF-15 showed satisfactory prognostic values for overall survival in patients with AL amyloidosis." (PMID 31434944, 2019). "Recent studies suggested that GDF15 contributes to myeloma cell growth and chemoresistance and, even more importantly, that high levels of GDF15 are correlated with a poor prognosis in MM patients." (PMID 29535427, 2018). "GDF15 enhances the tumor-initiating and self-renewal potential of myeloma cells, contributes to drug resistance in both stroma-dependent/independent MM cells, and promotes osteoclast differentiation while inhibits osteoblast differentiation." (PMID 29050213, 2017).